CD4 (CD4 molecule)
Diseases named in the same sentence as CD4 in open-access papers (continued):
Sharing a sentence is not in itself a finding about the gene and the disease.
COVID-19 (continued). "We show that COVID-19 convalescent patients mount robust CD4+ T cell responses to SARS-CoV-2 both following natural infection and after mRNA vaccination, however the exact clonotypes contributing to this response are largely divergent at the timepoint studied." (PMID 35533495, 2022). "There is evidence that CD4+ CTLs infiltrate/expand in the lung parenchyma of critically ill COVID-19 patients, and this infiltration/expansion is more prominent in the disease resolution phase." (PMID 36430210, 2022). "The percentage of CD3+CD4+ T cells expressing PD-1 exhibited a significant 2-fold increase in the severe COVID-19 group compared to the mild disease group (P = 0.0416)." (PMID 35860236, 2022). "KEGG pathway analysis of discriminative genes in CD4+ T cell leads to an important term, coronavirus disease—COVID-19 (hsa05171), directly supporting the reliability of our classifier that identified features highly related to COVID-19 infection." (PMID 35528178, 2022). "In this regard, two studies reported that 100% and 89% of convalescent COVID-19 patients had CD4 T cell reactivity, while only 70% and 69% developed CD8+ responses, respectively." (PMID 35865538, 2022). "The assessment of main T cell subsets in COVID-19 patients at different stages of the disease showed that the lowest levels of Th cells (CD3+CD4+) were observed during the acute disease stage in patients with a poor outcome." (PMID 35337053, 2022). "In the process of severe COVID-19, the inflammatory response increased, and the number of T cells such as CD4+ and CD8+ T cells decreased significantly, but activation of T cells increase." (PMID 36405695, 2022). "Individuals who recovered from severe disease presented almost overlapping results as those observed after stimulation with N and M. Moreover, they also displayed a higher percentage of TNF+IL-17+ within CD4+ T cells if compared to COVID-19 severe and HD." (PMID 35887351, 2022). "A study in Wuhan showed severe COVID-19 patients presented decreased regulatory T cells (CD3+ CD4+ CD25+ CD127low) proportion." (PMID 35874688, 2022). "Because of their connection to COVID-19 disease severity, we chose to perform these analyses in primary naive B cells, naïve CD4+ T cells, follicular helper T cells, and germinal center B cells from human tonsil, and circulating monocytes." (PMID 35659055, 2022). "We showed that the breadth and functionality of serologic or memory B and CD4+ T cell responses were dependent on the severity of the prior infection, even at 1 year post-COVID-19." (PMID 35392102, 2022). "The mRNA BNT162b2 vaccine elicited higher levels of antibody and CD4+ T-cell responses than those observed in mild COVID-19 patients." (PMID 35744768, 2022). "Memory T-cell responses at 1 year post-COVID-19 were most evident in CD4+ T cells in symptomatic patients, consistent with previous reports of memory T-cell responses at 8 months post-symptom onset." (PMID 35392102, 2022). "To broadly assess relationships between CD4+ T cell and antibody responses following COVID-19, we correlated individual parameters for all first time point blood draws by pairwise comparisons." (PMID 35857584, 2022). "This study demonstrates the presence of robust antigen-specific CD4+ T-cell responses specific for SARS-CoV-2 in the PBMCs of severe COVID-19 patients." (PMID 36248882, 2022). "Blood lymphopenia is a critical feature in patients with COVID-19, in which B-cells, CD4+ T-cells, and CD8+ T-cells have decreasing amounts." (PMID 35655192, 2022). "This review comprehensively discusses the adaptive immunity and COVID-19 severity by focusing on CD4+ and CD8+ T cell immunity." (PMID 36447262, 2022). "Patients experiencing COVID-19 moderate also displayed a high percentage of IFN-γ+IL-2+ within CD4+ T cells." (PMID 35887351, 2022).
COVID-19 (continued). "In contrast, in those over 50 years of age, we observed a significant decrease in the percentage of CD4+ T cells in blood following COVID-19, reflecting COVID-19 reports of lymphopenia." (PMID 35719387, 2022). "Similar to NK cells, the frequencies of IFN-γ-containing CD4+ T cells in response to in vitro stimulation was low in severe COVID-19 patients compared to controls." (PMID 35422799, 2022). "In this regard, we had the opportunity to evaluate humoral, B and CD4+ T cell–mediated spike-specific immune response in 14 (7 naive and 7 recovered from COVID-19) individuals before and 1 week after the administration of the booster dose." (PMID 35139036, 2022). "Other groups using similar assays to our OX40 assay have also found that the majority of recovered COVID-19 patients had detectable responses to pools of spike peptides, but with only a subset of patients having CD4 T cell responses to RBD epitopes." (PMID 36544780, 2022). "This indicates a link toward discordant CD4+ T-cell responses, which is a likely key element in the development of severe COVID-19." (PMID 36072602, 2022). "Our findings suggested that select subpopulations of T cells, including Th-17 cells, Treg cells, and CD4+ central memory T cells, were less responsive to COVID-19 plasma exosomes than CD4+ T cells, CD8+ T cells, and CD14+ monocytes." (PMID 36526691, 2022). "MRNA vaccine-induced CD8+ T cells appear to have crucial effects against COVID-19, especially before generating CD4+ T cell and antibody responses." (PMID 35418996, 2022). "CD4+ T cells primed in the setting of severe COVID-19 also appeared to have impaired Th1 memory formation, based upon decreased percentages of circulating CXCR3+CCR4– cells at early memory time points." (PMID 35857584, 2022). "Previous studies have focused on T cell responses in hospitalised COVID-19 patients but studies on naïve CD4 and CD8 T cells are scarce." (PMID 36078151, 2022). "It should be noted that the frequencies of spike-specific B and CD4+ T cells at month 8 are at least comparable to those observed in individuals who have recovered from COVID-19 before vaccination, confirming that they are still detectable at this time point." (PMID 35139036, 2022). "The course of severe COVID-19 is characterised by an increased inflammatory response with a marked reduction in the number of T cells, frequently of both CD4+ and CD8+ T cells." (PMID 35833134, 2022). "In summary, we found robust CD4+ AIM responses that were observed in COVID-19 patients, and these responses are more in severe patients compared to asymptomatic and mild patients." (PMID 36248882, 2022). "Lymphocytopenia and a low CD4+ T cell count are common futures in patients with severe COVID-19, which correlate with the severity of illness." (PMID 35736068, 2022). "BNT162b1 mRNA vaccine can protect against COVID-19 severe disease through multiple beneficial mechanisms, including increased antibody titers and induction of S-specific CD4+ and CD8+ T-cell." (PMID 36474011, 2022). "The results showed a desirable reduction in all types of lymphocytes, including NK cells, B lymphocytes, CD8 + T lymphocytes, and CD4 + T lymphocytes in COVID-19 patients, especially those with severe symptoms." (PMID 35842705, 2022). "In a recent study of COVID-19 patients with varying disease severity, it was observed that while nAb titers did not correlate with decreased disease severity, antigen-specific CD4 and CD8 T cell responses did44." (PMID 35606518, 2022). "Most BALF studies during pandemic COVID-19 have analysed cellularity characteristics (i.e. CD4 T-cells, CD8 T-cells, macrophages)." (PMID 35786088, 2022). "CD4+ T cells are strongly affected during COVID-19: their count in peripheral blood diminishes, circulation is affected, and there are changes in CD4+ T subset profiles and these cells present over-activation, exhaustion, and altered apoptosis." (PMID 36678366, 2022).
COVID-19 (continued). "In conclusion, this study highlights that both the magnitude and breadth of early SARS-CoV-2-specific CD4+ T cell responses correlated with milder disease outcomes in acute COVID-19 patients." (PMID 35806161, 2022). "CD4+ T cells from COVID-19 subjects that recognized these epitopes expressed CD45RO, a marker of antigen experience." (PMID 35857584, 2022). "During the acute phase of disease, the majority of SARS-CoV-2-specific CD4+ T cells in COVID-19 convalescents exhibited CD45RA–CCR7+ central memory phenotype." (PMID 35632823, 2022). "Patients with symptomatic COVID-19 often present with lymphopenia, and lymphocyte counts (total, CD4+ and/or CD8+) are proposed predictive factors for disease severity." (PMID 36614808, 2022). "When they were not stimulated, we detected an increase in the frequency of granzyme, IFN-γ, and CD107a of CD4+ T lymphocytes in patients with severe/critical COVID-19." (PMID 36359755, 2022). "A previous study manifested that COVID-19 patients with severe illness exhibited a significant decrease in CD4+ and CD8+ T cells." (PMID 36263178, 2022). "Patients with severe COVID-19 have marked reductions in the number and frequency of both CD4+ and CD8+ T cells, but increased activation of T cells." (PMID 35833134, 2022). "The pattern linked to severe COVID-19 is characterized by high PD-1 expression, low IL-2 and IFN-gamma production in CD4+ and CD8+ T cells, and poor IFN-alpha expression in classical and non-classical monocytes." (PMID 35860236, 2022). "As expected, expression of perforin and granzymes was to a large extent contained to cytotoxic CD8+ T cells, although some expression was also observed in lung-homing receptor-positive CD4+ T cells in COVID-19 and influenza patients." (PMID 35371005, 2022). "When the Th polarization of CD4+ T-cells was studied, COVID-19 patients compared to healthy controls showed a decreased median in the proportion of Th1: 4.8% (3.3–6.5) vs. 6.4% (4.9–8.2) (p = 0.011) and Th17: 4% (3.1–5.7) vs. 7% (3–10.6) (p = 0.018)." (PMID 35203509, 2022). "From these participants, one was infected with HIV with a low CD4 count, two were infected with COVID-19 after the visit at 2 weeks, and 15 were lost to follow-up; the GMT of anti-SRBD levels was 639 BAU/mL (95% CI 563–726)." (PMID 35455285, 2022). "COVID-19 patients with favorable outcomes had lower absolute CD4+ T cell counts during the acute stage of the disease compared to the control values." (PMID 35337053, 2022). "In COVID-19, the role of IL-7 is usually investigated through the prism of additional assessment of cellular responses (CD4+ and CD8+ lymphocytes)." (PMID 36430621, 2022). "SARS-CoV-2-specific CD4+ T cells can be detected as early as 2-4 days after the onset of symptoms 46, 47, which occurred in mild COVID-19 patients, accelerating viral clearance." (PMID 34975340, 2022). "In acute COVID-19 states, a significant decrease in T lymphocytes of both CD4+ and CD8+ cells is observed, with their simultaneous activation." (PMID 35458548, 2022). "Caspase-1 activity is also upregulated in CD4+ T cells of COVID-19 patients that were hospitalized, those with liver disease, and long-haulers." (PMID 35265086, 2022). "COVID-19 convalescents were found to have increased concentrations of IL-17 and counts of TNFα-producing CD4+ T helpers, while both the TNFα+ and IFNγ+ cell percentages were increased among cytotoxic T cells." (PMID 35337053, 2022). "We designed a prognostic model to determine the probability of contracting COVID-19 based on the vaccination status, CD4+ T-cell level, and age and sex of patients." (PMID 35340627, 2022). "On the contrary, functional defects in CD4+ T cells and exhaustion of CD8+ T cells are associated with severe COVID-19 outcomes." (PMID 36388890, 2022). "In contrast, levels of CD25+Foxp3+CD4+ regulatory T cells (Tregs) were found to be lower in COVID-19 patients." (PMID 36250073, 2022).
COVID-19 (continued). "CD8+ and CD4+ T cells were found to play an important role in the recovery of patients with critical COVID-19." (PMID 35214700, 2022). "Although COVID-19 leads to a dramatic decline in CD4+ T and CD8+ T cells in the acute phase, these cell populations in convalescent patients were not significantly different from those of uninfected people, indicating the full recovery from lymphopenia." (PMID 35464396, 2022). "Researchers found that both mild and severe COVID-19 patients had reduced levels of expression of CD4+ CD25+ CD127low Tregs and CD45RA+ Tregs." (PMID 36034704, 2022). "The mean CD4+ lymphocyte count before COVID-19 infection was higher compared to after being diagnosed with COVID-19, with values of 583 and 477 cells/mm3, respectively." (PMID 35371792, 2022). "Representative dot-plots illustrate the comparison of CD3+CD4+ T cells expressing IL-2 in blood samples treated with polyclonal stimuli from participants who developed mild or severe COVID-19 during the follow-up." (PMID 35860236, 2022). "We found for CD4+ T cells, COVID-19 plasma exosomes obtained from patients upon admission stimulated production of IL-6, IL-8, and TNF-α compared to plasma exosomes from non-COVID donors, with expression of IFNγ not being significantly affected." (PMID 36526691, 2022). "On the other hand, the COVID-19 vaccine induces the THαβ immune response and stimulates the development of long-term memory B cells, CD4 T cells, and CD8 T cells." (PMID 36583218, 2022). "It has been reported that the early stages of COVID-19 are characterized by the decreased levels of CD3+/CD4+/CD8+ cells." (PMID 35387350, 2022). "Lower circulating CD27+CD28+CD45RA+CCR7+ ‘naïve’ CD4+ T cell counts predicted a poor prognosis in patients with acute COVID-19." (PMID 35632823, 2022). "We thus assessed the level of CD4 T-cell death by detecting caspase activity using flow cytometry after ex vivo culture and found that COVID-19 patients’ CD4 T cells were more prone to die than those of healthy donors (HDs), consistent with our recent report." (PMID 36030261, 2022). "We found that COVID-19 moderate patients develop polyfunctional CD4+ T cells compared to patients experiencing a severe infection, that in turn display a higher percentage of CD107a+ cells." (PMID 35887351, 2022). "On the other hand, recent studies have shown that patients suffering from COVID-19 present with a reduced number of CD4 and CD8 cells, resulting in a declined adaptive form of immunity." (PMID 36560789, 2022). "Patients with long COVID had reduced CD4+ and CD8+ effector memory (EM) cell numbers; this T cell perturbations persisted for several months after mild COVID-19 and was associated with long COVID symptoms." (PMID 35214624, 2022). "We sorted a median of 389 AIM+ CD4 T cells (machine counts; range, 375–2138) per specimen from the 5 COVID-19 convalescent subjects." (PMID 35133988, 2022). "To explore the T cells primed for anti-viral immune response, we evaluated the SARS-CoV-2 specific CD4+ T cells in the TCR-dependent AIM assay in COVID-19 patients of different disease severity." (PMID 36248882, 2022). "A previous study reported that frequencies of SARS-CoV-2-specific IFN-γ secreting CD4+ T cells are lower in COVID-19 patients requiring intensive care, compared to those in recovered patients." (PMID 35107382, 2022). "It has been shown that the mRNA-based COVID-19 vaccine induces Spike-specific CD4+ and CD8+ T cells." (PMID 37118289, 2022). "Using our stringent data-driven statistical algorithm alongside replicate analysis, we identified SARS-CoV-2 spike-specific memory CD4+ TCRs present after COVID-19 and after mRNA vaccination in all CCPs tested (n = 10)." (PMID 35533495, 2022). "In contrast to the uncomplicated convalescent COVID, acute disease featured much more variable CD4+ T cell responses in 77% of acute COVID-19 patients than 100% in convalescents, and 27% of CD4+ responses were designated weak." (PMID 35401519, 2022).
COVID-19 (continued). "On the other hand, we observed a decrease in the CD8+ T cells and increase in the CD4+ T cell population in the COVID-19 patients." (PMID 36532041, 2022). "Compared with other pulmonary myeloid cell populations in COVID-19, the transcriptome of the CD4+ macrophage subset suggests low cytokine production but high capacity to activate local T cells through costimulation and antigen presentation." (PMID 35446789, 2022). "Th17 in COVID-19: Th17 is an IL-17-producing CD4+ T-cell subsets, which can be recognized by their production of interleukin-17 (IL-17)." (PMID 36034704, 2022). "Surprisingly, there is data that perhaps the COVID-19 virus reduces the concentration of CD4 cells and the concentration of CD8 cells in affected people." (PMID 35911334, 2022). "Further, ChAadOx1 nCoV-19 vaccination led to enhanced IFN-γ production (15 DAV) and an increase in activated T CD4+ naïve cells in noCOVID-19 individuals in contrast with COVID-19 individuals." (PMID 36146723, 2022). "In response to polyclonal in vitro stimulation, the percentage of CD3+CD4+IL-2+ T cells showed a significant 4-fold decrease in the group that during the follow-up developed severe COVID-19 compared to participants experiencing mild symptoms (P = 0.0085)." (PMID 35860236, 2022). "Studies of acute and convalescent COVID-19 patients have observed that T cell responses are associated with reduced disease, suggesting that SARS-CoV-2-specific CD4+ and CD8+ T cell responses contribute significantly to infection control and resolution." (PMID 34983950, 2022). "Together, our work shows that complete vaccination against COVID-19 induces broad spike-specific CD4+ and CD8+ T cell immunity by different vaccination regimens that resembles T cell responses after natural SARS-CoV-2 infection." (PMID 36318037, 2022). "Preliminary studies have shown that leronlimab treatment of COVID-19 patients induced a reduction of plasma IL-6, restoration of the CD4/CD8 ratio, and resolution of SARS-CoV-2 plasma viremia." (PMID 35572540, 2022). "Consistent with this, we found hospitalized COVID-19 patients with mild disease had higher numbers of expanded clones in both CD4+ and CD8+ subsets, and the mean clone size was higher within the CD8+ subset." (PMID 35216673, 2022). "There was a significant drop in CD4+ TFH-TH1 cells at hospitalization among COVID-19 patients as compared to healthy controls, which consistently increased throughout the infection, reaching a level at 6-7 months that was comparable to healthy controls." (PMID 36003367, 2022). "During severe COVID-19 disease, activated CD4+ T cells reactive to SARS-CoV-2 C-terminal S and NCAP were also detectable and frequencies of activated, reactive T cells were generally much higher (1.8–2.2% CD154+CD137+CD4+ during COVID-19)." (PMID 35359967, 2022). "IL-22-expressing CD4+ T cells (TH22-like) were relatively enriched in asymptomatic or mild COVID-19 cases." (PMID 36119105, 2022). "The use of PBMCs of COVID-19 naïve individuals didn’t reveal significant differences in cytokine-producing CD4 and CD8 T cells between recombinant viruses and the LAIV control." (PMID 35891306, 2022). "Peripheral circulation T cell lymphopenia affecting both CD4+ and CD8+ T cells is a universal finding in case series of COVID-19 and is associated with severe disease." (PMID 35965490, 2021). "Using in silico-predicted HLA-class I and II peptide pools, CD4+ T cell responses to SARS-CoV-2 were demonstrated in all volunteers who had recovered from COVID-19 and CD8+ responses were demonstrated in 70%10." (PMID 33824342, 2021). "PolyPEPI-SCoV-2-specific, polyfunctional CD8+ and CD4+ T cells were detected in each of the 17 asymptomatic/mild COVID-19 convalescents' blood against on average seven different vaccine peptides." (PMID 34249101, 2021). "A study found that older age, late diagnosis, low CD4 cell count, and treatment-naive status were potential determinants of COVID-19 incidence amongst HIV patients." (PMID 34015893, 2021).